CCL3 (C-C motif chemokine ligand 3)
Diseases named in the same sentence as CCL3 in open-access papers (continued):
Sharing a sentence is not in itself a finding about the gene and the disease.
HIV-1 infection (28 papers, 2007 to 2025). The type species of lentivirus and the etiologic agent of acquired immunodeficiency syndrome (AIDS). "CCL7, CCL2, CCL3 and others are overexpressed during HIV-1 infection, contributing to the secretion of more pro-inflammatory cytokines, leading to chronicity of the infectious process observed in HIV-positive individuals." (PMID 33557210, 2021). "Although several studies have investigated the influence of HIV-1 infection and disease progression on circulating levels of CCL3, CCL4 and CCL5, results have been contradictory." (PMID 34987508, 2021). "We report that decidual mononuclear cells naturally produce large amounts of chemokines, and that R5 HIV-1 infection significantly enhances production of the β-chemokines CCL-3 and CCL-4." (PMID 21767373, 2011). "We speculate that the binding property of CCL4 and CCL3 to the CCR5 HIV-1 co-receptor may however result in a beneficial effect by preventing potential HIV-1 infection." (PMID 35967369, 2022). "The findings from this study have shown that the MIP-1α/CCL3 chemokine levels were associated with S. haematobium egg counts at baseline before treatment, but not with HIV-1 infection status." (PMID 19852800, 2009). "The results of our study show that the MIP-1α/CCL3 levels were positively associated with S. haematobium egg counts at baseline but not with HIV-1 infection status." (PMID 19852800, 2009). "HIV-1 infection of human macrophages leads to the release of β-chemokines including CCL2, CCL3, CCL4, and CCL5." (PMID 38005838, 2023). "CCL4, together with CCL5 (RANTES) and CCL3, is produced by CD8+ T cells and is a suppressive factor for HIV-1 infection; recombinant CCL4, CCL5 and CCL3 block HIV-1 infection of susceptible cells in vitro." (PMID 35967369, 2022). "Study by Wen and colleagues also showed that expression of CCL3, CCL4 and CCL5 decreased in U937 promonocytes in response to HIV-1 infection." (PMID 17684570, 2007). "In addition to CCL2, other CC chemokines, namely CCL3, CCL4 and CCL5, are constitutively released by MDM and their production can be further increased following HIV-1 infection of these cells." (PMID 25608886, 2015). "The first encounter between the fields of HIV and chemokines occurred unexpectedly at the end of 1995 with the discovery that three chemokines of the CC family, RANTES (CC-chemokine ligand 5 or CCL5), MIP-1α (CCL3) and MIP-1β (CCL4), act as potent and specific natural inhibitors of HIV-1 infection." (PMID 21284904, 2011). "Thus, CCL-3 and CCL-4 release by cultured decidua basalis mononuclear cells was enhanced by R5 HIV-1 infection." (PMID 21767373, 2011). "CCL3, CCL4, CCL5 and CXCL12 are important natural inhibitors of HIV-1 infection, and it possible that the activation of chemokine receptors may stimulate chemokine expression." (PMID 21264298, 2011). "Luminex analysis showed that CCL-3 and CCL-4 release was increased by R5 HIV-1 infection." (PMID 21767373, 2011). "In this study we found that schistosomiasis infection being depicted by high egg output significantly upregulated the plasma levels of MIP-1α/CCL3 irrespective of HIV-1 infection status." (PMID 19852800, 2009). "The CC-chemokines CCL3, CCL4 and CCL5 have been found to block the entry of CCR5-tropic HIV into host cells and to suppress the viral replication in vitro, but the in vivo role of endogenous CC-chemokines in HIV-1 infection is still incompletely understood." (PMID 17684570, 2007). "Here, we found that secretion of the β-chemokines CCL-3 and CCL-4 was significantly upregulated during R5 HIV-1 infection of decidual mononuclear cells, but not during X4 HIV-1 infection." (PMID 21767373, 2011).
malaria (27 papers, 2008 to 2025). Malaria is a serious and sometimes fatal disease caused by a parasite that commonly infects a certain type of mosquito which feeds on humans. "CCL3, a chemokine typically downregulated in asymptomatic malaria in humans, has been associated with the development of severe disease, including cerebral and placental malaria." (PMID 41279035, 2025). "Indicating that the protection against malaria associated with this genotype may be mediated by CCL3." (PMID 33424841, 2020). "The concurrent increase in CCL3 and IL-1β underscores the need to further investigate whether these immune responses confer enhanced parasite control, increased risk of immunopathology, or represent a unique adaptation of chimpanzees to chronic malaria exposure." (PMID 41279035, 2025). "We show during malaria age is associated with increased inflammatory chemokines CCL2, CCL3, CXCL8, CXCL9, along with CRP, and IDO, which associate with symptoms." (PMID 41027884, 2025). "Increased TNF, IFN-γ, IL-6, IL-10, IL-17, CCL2, and CCL3 levels and decreased IL-7 levels were observed in malaria monoinfection compared to dengue virus monoinfection." (PMID 36716305, 2023). "For malaria and virus coinfections, increased TNF, IFN-γ, IL-6, and CCL4 levels and decreased IL-4, IL-7, IL-12, TGF-β, and CCL3 levels were observed in malaria coinfections compared to dengue monoinfection." (PMID 36716305, 2023). "High levels of CCL3 are harmful to malaria, COVID‐19, and TB‐infected individuals but beneficial for HIV‐infected individuals." (PMID 38099246, 2023). "Gabonese children with severe malaria were found to have elevated levels of CCL3 and CCL4 in their circulation." (PMID 32373101, 2020). "Based on our data CXCL10, TNF-α, CCL3, IL-8, and IL-6 may be investigated as potential markers to assess malaria severity and protection." (PMID 33424841, 2020). "We evaluated the expression of CXCL10, TNF-α, CCL2, CCL3, IL-8, and IL-6 among 74 volunteers, from a pool of 923, with one (HbAS and HbAC), two (HbSS, HbSC, HbCC) and no (HbAA) copies of the Hb allele variant S and/or C with (+) and without (-) malaria." (PMID 33424841, 2020). "Increased TNF, IFN-γ, IL-1, IL-2, IL-6, IL-10, TGF-β, CCL2, CCL3, and G-CSF levels and decreased IL-5, IL-12, IL-17, and CCL11 levels were observed in malaria monoinfection compared to intestinal parasite monoinfection." (PMID 36716305, 2023). "For cytokines IL-6, IL-1RA, IL-10 and IL-11 and chemokines CXCL1, CXCL8, CXCL10, CCL3 and CCL2, significantly higher concentrations were found in plasma samples of malaria patients compared to healthy controls." (PMID 34359826, 2021). "Previous studies have reported increased levels of CCL3, as well as CCL2 and IL-8, have been reported in pregnant women with malaria." (PMID 33424841, 2020). "In another study, IL-8/CXCL8 was elevated in CSF of non-fatal CM cases of P. falciparum-infected children, while MCP-1/CCL2, MIP-1α/CCL3, MIP-1β/CCL4, and RANTES/CCL5 levels were comparable to malaria-free controls." (PMID 28775960, 2017). "Plasma levels of inflammatory cytokines (IFNα, IFNγ, TNF, IL-6) and chemokines (CCL2, CCL3, CCL4, CXCL10) were significantly higher during severe malaria compared to convalescence." (PMID 27792766, 2016). "Inflammatory chemokines CXCL10, CCL2, and CCL3 as well as cytokines, TNF-α, IL-8, and IL-6 were differentially expressed in individuals with different hemoglobin genotypes that were infected or uninfected with malaria parasites." (PMID 33424841, 2020). "Circulating CXCL10, CCL3, IL-8, TNF-α, and IL-6 could be used as potential biomarkers for malaria severity among individuals with hemoglobinopathies." (PMID 33424841, 2020). "It was also determined that malaria outcomes could be altered based on the crosstalk between inflammatory cytokines (CXCL10, CCL3, IL-8, TNF-α, and IL-6) and Hb genotypes." (PMID 33424841, 2020).
malaria (continued). "In severe malaria in Malawian children, the inflammatory monocyte subset was expanded and activated with higher plasma levels of inflammatory cytokines (IFNα, IFNγ, TNF-α, IL-6) and chemokines (CCL2, CCL3, CCL4, CXCL10) than in convalescence." (PMID 30581439, 2018). "In addition, in vitro differentiated syncytiotrophoblasts have been shown to produce CCL3, CCL4 and CXCL8 in response to stimulation with malaria hemozoin, which is highly abundant in the placenta during PM." (PMID 24476686, 2014). "However, for the malaria group, four distinct correlation patterns were observed; first pattern (CCL4, CCL2, CCL3, IL12 and IL2), second pattern (IL-17A, IL-1β, CCL11, IL4), third pattern (IL5, IL7, IL13), and fourth pattern (IL1RA, CXCL10, TNFα, IL2R, CXCL9, IL6)." (PMID 35811678, 2022). "We report high plasma levels of proinflammatory cytokines and chemokines (IFNγ, TNF, IL-6, CCL2, CCL3, CCL4, CXCL10) in severe malaria patients compared to baseline uninfected follow-up, which matched that of Py infection in mice in which we could conduct a temporal analysis." (PMID 27792766, 2016). "Pro-inflammatory chemokines (CXCL10, CCL2, and CCL3) and cytokines (TNF-α, IL-8, and IL-6) were reported to mediate severe malaria and SCD separately but have not been examined in SCD individuals infected with malaria." (PMID 33424841, 2020). "Furthermore, we previously showed that different sickle Hb genotypes with or without malaria parasites have different levels of CXCL10, CCL3, IL-8, TNF-α, and IL-6 in the blood." (PMID 37108709, 2023).
diabetes (26 papers, 2012 to 2026). "Research on animals has suggested that CCL3 is involved in the neuropathic pain caused by diabetes, suggesting that it may be a prominent target for pain treatment." (PMID 39457105, 2024). "CCL3 also causes hypersensitivity by directly sensitizing primary sensory neurons, and is responsible for disturbances in nociception processes caused by nerve injury and diabetes." (PMID 34681732, 2021). "Interestingly, CCL3 treatment lowered serum IgG1 in diabetic mice to levels similar to those of nondiabetic controls, suggesting a beneficial CCL3-induced modulation of dysregulated adaptive immune responses that are commonly associated with diabetes." (PMID 41597195, 2026). "To date, only one study has considered the role of CCL3 in human diabetes." (PMID 39457105, 2024). "Additionally, direct neutralization of CCL3 or CCL9 decreases pain-related behaviors in diabetes- and paclitaxel-induced neuropathy." (PMID 32691345, 2020). "In particular, CCL3 and CCL4 encoding small CC chemokines known as macrophage inflammatory protein 1α and 1β, respectively, were well-recognized as key mediators of both diabetes and atherosclerotic cardiovascular disease." (PMID 28710368, 2017). "Collectively, histopathological analysis across multiple organs demonstrates that topical CCL3 treatment, even at 10-fold higher dose, does not induce systemic organ toxicity or exacerbate diabetes-associated tissue pathology, supporting its favorable safety profile in this model." (PMID 41597195, 2026). "Thus, CCL3 may constitute a common target for effective pharmacotherapy in obese individuals, who suffer from other ailments, such as diabetes and hypersensitivity." (PMID 39457105, 2024). "In people without diabetes SRA1 expression was associated with CCL3 (r = 0.298, p = 0.036), CCL8 (r = 0.344, p = 0.021), CXCL11 (r = 0.400, p = 0.003), TNF-α (r = 0.317, p = 0.030), TGF-β (r = 0.514, p < 0.0001), IL13 (r = 0.310, p = 0.028), and IL18 (r = 0.547, p < 0.0001)." (PMID 34685582, 2021). "A significant reduction in the levels of IL-5, CCL-3/MIP-1α, and CCL-11/eotaxin was observed in the lungs of allergen-challenged mice under condition of diabetes." (PMID 29849493, 2018). "In another NOD mouse model, an elevated ratio of CCL3 to CCL4 in the pancreas was correlated with destructive insulitis and progression to diabetes." (PMID 27553774, 2016). "Overall, systemic immunological profiling supports the safety of topical CCL3 therapy in diabetic mice, as treatment did not exacerbate circulating markers, including IgE and CRP which are commonly elevated in diabetes and linked to disease complications." (PMID 41597195, 2026). "Recently, it was postulated that C–C (CCL2, CCL3), C–X–C (CXCL1, CXCL5, CXCL12), and X–C (XCL1) motif chemokine ligands play a crucial role in the development of neuropathic pain, including the pain accompanying diabetes." (PMID 29593735, 2018). "Therefore, the goal of our study was to evaluate the participation of macrophage inflammatory protein-1 (MIP-1) family members (CCL3, CCL4, CCL9) in a streptozotocin (STZ)-induced mouse model of diabetic neuropathic pain." (PMID 29593735, 2018). "In summary, while CCL3 contributes to the development of type 1 DM, CCL4 might play a protective role in some experimental diabetes, especially the NOD type 1 DM model." (PMID 27553774, 2016). "In NOD.Scid recipients, the neutralization of CCL3 with specific antibodies following transfer of diabetogenic T cells delayed the onset of diabetes, while the injection with anti-CCL4 mAb did not." (PMID 27553774, 2016). "One transcript, CCL3, although increased in the mice, was not increased in individuals in the FHS with these variables but was associated with other factors, such as diabetes." (PMID 26148065, 2015). "Importantly, administration of CCL3 at either the 1 μg or 10 μg dose did not further alter circulating WBC levels, indicating that CCL3 treatment does not exacerbate diabetes-associated leukocytosis." (PMID 41597195, 2026).
diabetes (continued). "Additionally, we have shown that in STZ-induced diabetes, the pain perception threshold to mechanical and thermal stimuli is lowered, which correlates with microglial activation and an increase in the expression of two MIP-1 family members (CCL3 and CCL9)." (PMID 29593735, 2018). "Moreover, a decreased intra-pancreatic CCL3 to CCL4 ratio was also observed in nonobese diabetes-resistant mice." (PMID 27553774, 2016).
liver fibrosis (26 papers, 2010 to 2024). "In mouse models of liver fibrosis, induced by CCl4 or by a methionine- and choline-deficient diet, blocking CCL3 or CCL5 decreased HSC activation and reduced fibrosis." (PMID 39063116, 2024). "Even in patients infected with low parasite burden and without severe clinical symptoms, the serum concentration of CCL3 was positively associated with the intensity of the liver fibrosis." (PMID 33777015, 2021). "Reduced liver fibrosis in CCL3−/− mice was associated with altered expression of Col1a1, TIMP1, and MMP9 (P<0.05)." (PMID 23799074, 2013). "Along with the data in the MCD model histological analysis of Sirius red staining revealed reduced liver fibrosis in CCL3 deficient mice after chronic CCl4 treatment (P<0.001)." (PMID 23799074, 2013). "In fact, peripheral blood mononuclear cells from schistosome-infected patients with ultrasonographically-defined hepatosplenomegaly produced high levels of CCL3 when exposed to egg antigen; and marked them as group under greater risk of developing severe disease with hepatic fibrosis." (PMID 30546364, 2018). "CCL3, also known as macrophage inflammatory protein-1α, is responsible for liver immune cell infiltration and therefore mediates experimental liver fibrosis." (PMID 33005011, 2021). "The findings were further confirmed in another study where the plasma concentrations of CCL3 and that of other chemokines, namely CCL24, sTNFR1 and MIF (migration inhibitory Factor), were associated with hepatic fibrosis progression." (PMID 30546364, 2018). "Taken together, our findings present evidence that the CC chemokine CCL3 is a crucial mediator of experimental liver fibrosis." (PMID 23799074, 2013). "The effects of CCL3 make this CCR1/CCR5 ligand attractive for further evaluation in experimental liver fibrosis." (PMID 23799074, 2013). "In line with these previous data, we here show that CCL3 is an important mediator of experimental liver fibrosis by its dual effects on hepatic stellate cells and intrahepatic immune environment." (PMID 23799074, 2013). "The correlation of CCL3 with hepatic fibrosis may be related to the fact that this chemokine stimulates the production of IL-13, which is considered a pro-fibrotic cytokine." (PMID 33777015, 2021). "Also, some previous studies indicated that, while inhibition of CCR1 and CCR5 inhibited the progression of liver fibrosis in mice, concentrations of CCl4 and CCl3 increased in mouse liver fibrogenesis models and cirrhotic patients." (PMID 33042108, 2020). "It is similar ERK2−/− and CCL3−/− mice had less degree of liver fibrosis." (PMID 32471201, 2020). "Furthermore, other CCRs such as CCR1 and CCR5, via CCL3/MIP1α, CCL4/MIP1β and CCL5/RANTES interaction have been implicated in liver fibrosis attributed to Ly-6Chigh monocytes recruitment or stellate cells activation, respectively." (PMID 31849997, 2019). "CCL3 has been shown to be a mediator of experimental liver fibrosis in mice." (PMID 27992443, 2016). "Deletion of CCL3 exhibited reduced liver fibrosis compared to their wild-type counterparts." (PMID 23799074, 2013). "In conclusion, our results define the chemokine CCL3 as a mediator of experimental liver fibrosis." (PMID 23799074, 2013). "MCD-fed CCL3−/− animals showed significantly reduced liver fibrosis compared to CCL3+/+ mice." (PMID 23799074, 2013). "However, individual chemokine concentrations, such as CCL3, CCL7, CCL24 (eotaxin-2), Macrophage Migration Inhibitory Factor (MIF), and soluble TNF-α receptor 1, were positively associated with Schistosoma-related liver fibrosis." (PMID 30619332, 2018). "In mice, the elimination of neutrophils or the deletion of neutrophil-derived soluble molecules (IL-8, IL-18, IL-17, CCL3, CCl4, and CCL2) attenuates the development of hepatic fibrosis." (PMID 39063116, 2024).
liver fibrosis (continued). "CCR2 (a receptor for CCL2) and CCR5 (a receptor for CCL3 and CCL4) have been proposed to be targets for antifibrotic therapy due to their ability to promote liver fibrosis and macrophage infiltration." (PMID 35662287, 2022). "Among these hub genes, some are cytokines and chemokines closely related to liver fibrosis (IFNG, CCL3, CCL4, CCL5, and CXCR4)." (PMID 35903097, 2022). "HSCs express a multitude of chemokines, including the CC chemokines CCL2, CCL3, and CCL5, which are involved in cell chemotaxis and liver fibrosis." (PMID 25076488, 2014). "CCL3 is increased after MCD feeding; hence we tested if deletion of CCL3 has an impact on liver fibrosis." (PMID 23799074, 2013). "CCL3 is a ligand for CCR1 and CCR5 that fosters the progression of hepatic fibrosis." (PMID 39063116, 2024). "Moreover, CCR1 and CCR5, receptors for the chemokines CCL3/MIP1α, CCL4/MIP1β and CCL5/RANTES, were found to promote liver fibrosis in mice." (PMID 23259611, 2012). "Moreover, CCR1 and CCR5, receptors for the chemokines CCL3/MIP1α, CCL4/MIP1β and CCL5/RANTES, promote liver fibrosis in mice." (PMID 20548789, 2010). "Here, we could show that mice lacking CCL3 showed significantly reduced MCD- and CCl4- induced liver fibrosis compared to CCL3+/+ mice, as determined by quantification of Sirius red staining and biochemical measurement of hepatic hydroxyproline contents." (PMID 23799074, 2013).